COL1A1 (collagen type I alpha 1 chain)
Diseases named in the same sentence as COL1A1 in open-access papers (continued):
Sharing a sentence is not in itself a finding about the gene and the disease.
cyst (3 papers, 2012 to 2025). A sac-like closed membranous structure that may be empty or contain fluid or amorphous material. "In contrast, explanted lung tissue from cases 1 and 2 who underwent lung transplantation contained KRT17-positive cells that were localized near COL1A1-positive cells and in some regions appeared to line the cyst-like structures revealed by standard histology." (PMID 33257409, 2020). "In contrast, MTTV-Cre-mediated conditional deletion of Pkd1 results in liver cysts by 10 weeks-of-age, suggesting that the lack of liver cysts in our study was a consequence of limitations of the Col1a1(3.6)-Cre or the need for additional time for cyst development in the liver." (PMID 23029375, 2012). "The non-lethality of Col1a1(3.6)-Cre;Pkd1flox/flox mice establishes a new model to study abnormalities in bone development and cyst formation in pancreas and kidney caused by Pkd1 gene inactivation." (PMID 23029375, 2012). "In addition to skeletal abnormalities, we found that Col1a1(3.6)-Cre-mediated deletion of Pkd1 resulted in cyst formation in the kidney and pancreas." (PMID 23029375, 2012). "RT-qPCR results suggested that both COL1A1 and MFAP4 were significantly upregulated in biliary atresia compared to the total functional cyst liver tissue (P < 0.05)." (PMID 40492258, 2025). "Unexpectedly, we found that Col1a1(3.6)-Cre was not bone specific and resulted in deletion of Pkd1 in multiple tissues, leading to cyst formation in the kidney and pancreas, but not the liver of adult mice." (PMID 23029375, 2012). "In contrast, no cyst formation was observed in the kidney or pancreas of age-matched control Pkd1flox/flox or heterozygous Col1a1(3.6)-Cre;Pkd1flox/+ mice." (PMID 23029375, 2012). "The reason for the absence of cyst formation in the liver is not clear from our studies, because Col1a1(3.6)-Cre is expressed in the liver and results in excision of the Pkd1 flox allele in this tissue, similar to the pancreas and kidney." (PMID 23029375, 2012). "Hematoxylin-eosin (H&E)-stained sections showed no cyst formation in liver tissues from all of three groups, in spite of 35% and 54% reduction in Pkd1 mRNA expression in heterozygous Col1a1(3.6)-Cre;Pkd1flox/+ and homozygous Col1a1(3.6)-Cre;Pkd1flox/flox mice, respectively." (PMID 23029375, 2012).
dermatosparaxis (3 papers, 2019 to 2025). "Compact “hieroglyphs” have been reported from dermal tissue from patients with arthrochalasia caused by COL1A1 mutations and moderately severe cases of dermatosparaxis." (PMID 36421833, 2022). "Other types include kyphoscoliotic EDS (kEDS), which causes severe muscle weakness due to PLOD1 mutations, arthrochalasia EDS (aEDS) with extreme joint laxity resulting from COL1A1 or COL1A2 mutations, and dermatosparaxis EDS (dEDS) with fragile skin due to ADAMTS2 mutations." (PMID 40542421, 2025).
endometrial cancer (3 papers, 2020 to 2024). Primary or metastatic malignant neoplasm involving the endometrium (mucous membrane that lines the endometrial cavity). "ALKBH5 promoted the activity of endometrial cell via upregulation of COL1A1 and MMP9 expression, which finally promoted the progression of endometrial cancer." (PMID 32913456, 2020).
endometriosis (3 papers, 2022 to 2023). The growth of functional endometrial tissue in anatomic sites outside the uterine body. "In endometriosis, this condition has been related to the aberrant transcriptional activation of Col1a1 and Col1a2 genes, proving to be critical factors for endometrial receptivity." (PMID 36830911, 2023). "Among the 15 DEPs, COL1A1, COL6A2, and NID2 are among the proteins with strong interactions, and MT2A, TYMP, COL1A1, and COL6A2 have already been associated with endometriosis." (PMID 36232817, 2022).
esophageal squamous cell carcinoma (3 papers, 2021 to 2023). Esophageal squamous cell carcinoma (ESCC) is a type of esophageal carcinoma (EC) that can affect any part of the esophagus, but is usually located in the upper or middle third. "miR-133a-3p inhibited cell proliferation, invasion, and migration by targeting COL1A1, and promoted apoptosis of Esophageal Squamous Cell Carcinoma." (PMID 37624253, 2023).
hypospadias (3 papers, 2020 to 2025). Hypospadias is the displacement of the urethral meatus on the ventrum of the penis. "In this study, we determined the expression of collagen 1 (COL1A1) and COL6A1 in patients with hypospadias and associated them with the severity of penile curvature." (PMID 33261612, 2020). "Therefore, we determined the expression of collagen 1 (COL1A1) and COL6A1 in patients with hypospadias and associated them with the severity of penile curvature." (PMID 33261612, 2020). "Our previous study showed that the expression of COL1A1 and COL6A1 were significantly downregulated in the hypospadias patients with more severe chordee than the milder one (Indonesian)." (PMID 38041174, 2023). "Here, we are able to show downregulated COL1A1 and COL6A1 expression in hypospadias patients with moderate and severe penile curvature." (PMID 33261612, 2020). "We also investigated the significant difference in COL1A1 and COL6A1 expression among groups based on penile curvature in the hypospadias group." (PMID 33261612, 2020). "Aberrant COL1A1 and COL6A1 expression might affect abnormalities in darto tissue and penile curvature severity in hypospadias patients." (PMID 33261612, 2020). "Therefore, this study aims to investigate the distinct histopathological profiles and expression of COL1A1 (collagen type 1), COL3A1 (collagen type 3), and ELN (elastin) in proximal and distal ventral dartos of patients with hypospadias compared to those with a normal penis." (PMID 39964742, 2025). "This study aims to investigate the distinct histopathological profiles and expression of COL1A1 (collagen type 1), COL3A1 (collagen type 3), and ELN (elastin) in proximal and distal ventral dartos of patients with hypospadias compared to those without hypospadias." (PMID 39964742, 2025).
infarction (3 papers, 2024 to 2025). A localised pathological necrosis of tissue resulting from obstruction of the blood supply usually by a thrombus, an embolus, or vascular torsion. "Although the elevated Piezo1 level did not significantly upregulate Col1a1, histological evaluations showed overexpression of PIEZO1 resulted in a larger infarction size (19.6%) and smaller LV wall thickness (1.7 mm) compared to MI+P (17.4%, 2.0 mm) and MI+P+oeCtrl (17.3%, 2.0 mm)." (PMID 40344385, 2025).
Infertility (3 papers, 2020 to 2026). "COL1A1 overexpression was also observed in the eutopic endometrium of infertile women with endometritis." (PMID 32545766, 2020).
intervertebral disc degeneration (3 papers, 2017 to 2024). "An increase in miR-625-5p targeting COL1A1 mRNA results in a decrease in the COL1A1 transcript and eventually contributes to the pathological process of intervertebral disc degeneration." (PMID 35008515, 2021).
juvenile osteoporosis (3 papers, 2017 to 2019). "Indeed, since cases of juvenile osteoporosis have been ascribed to inactivating mutations of the type 1 collagen (COL1A1), ERalpha (ERα), aromatase (CYP19), and low-density lipoprotein receptor-related protein 5 (LRP5) genes, the sequencing of these genes can be performed." (PMID 29058226, 2017).
malignant astrocytomas (3 papers, 2020 to 2023). "COL1A1 expression affects cell migration, survival, and recurrence in diabetic retinopathy (DR) and malignant astrocytoma patients." (PMID 38004422, 2023). "COL1A1, collagen type I alpha 1 chain, has been identified as an invasion‐related gene in malignant astrocytomas." (PMID 34034744, 2021). "In addition, the close association observed here between increased VEGFA and COL1A2, COL3A1 and COL1A1 expression in GBM, might also contribute to explain the effect of VEGFA on inducing collagenase expression and remodeling the tumor microenvironment in malignant astrocytomas (i.e. GBM)." (PMID 32647207, 2020).
myocardial ischemia (3 papers, 2021 to 2023). A disorder of cardiac function caused by insufficient blood flow to the muscle tissue of the heart. "Eight genes (Aif1, Apoe, Arg1, Col1a1, Gpx7, Hmox1, Mmp14, and Sirpa) were significantly differentially expressed in the rat myocardial ischemia-reperfusion model." (PMID 36826575, 2023). "After long-term myocardial ischemia (28 days after injury), the expression of fibrotic genes (e.g., COL1A1 and LOX) was dramatically enhanced, leading to increased ECM production and deposition, as revealed by immunostaining of type I collagen." (PMID 36089604, 2022). "Morphological observation and expression of the fibrotic genes COL1A1 (Col1) and ACTA2 (αSMA) were used to validate myocardial ischemia." (PMID 32845445, 2021).
oral squamous cell carcinoma (3 papers, 2016 to 2025). "Regulating COL1A1 expression directly through miR-133a-3p in oral squamous cell carcinoma suppressed mitosis, proliferation, and invasion of cancer cells." (PMID 40076457, 2025).
pancreatitis (3 papers, 2015 to 2019). Inflammation of the pancreas. "Expression analyses of fibrosis, pancreatitis, or desmoplasia associated markers (α-SMA, Shh, COX-2, Muc6, Col1a1, and Ctgf) were performed by IHC and/or qRT-PCR." (PMID 25803032, 2015). "(D) qRT-PCR for transgenic Kras*, Fn1, Col1a1, Col3a1, Shh, Hbegf, Ereg, Areg, Tgfα and Egf in littermate control and iKras*;CD11b-DTR pancreata 3 weeks post pancreatitis and in iKras*;CD11b-DTR pancreata following DT treatment for 3 days and 1 week." (PMID 28980940, 2017).
pelvic organ prolapse (3 papers, 2019 to 2022). Abnormal descent of a pelvic organ resulting in the protrusion of the organ beyond its normal anatomical confines. "We investigated whether single nucleotide polymorphisms (SNPs) of collagen type 1 alpha 1 (COL1A1), collagen type 3 alpha 1 (COL3A1), and lysyl oxidase-like (LOXL) 1 and 4 were associated with the onset of pelvic organ prolapse (POP) in Japanese women." (PMID 33413618, 2021).
periodontal disease (3 papers, 2021 to 2026). "Analogous changes in the COL1A1 gene may compromise the structural stability of dental tissues, increasing susceptibility to both dental caries and periodontal disorders." (PMID 40310312, 2025). "Studies have indicated that those with certain polymorphisms in COL1A1 or MMP may be more likely to experience more severe bone loss as periodontal disease progresses." (PMID 40310312, 2025). "Several studies have highlighted the importance of COL1A1 in both healthy periodontal tissues and in the pathogenesis of periodontal disease." (PMID 41502450, 2026). "Alterations in COL1A1 expression have been shown to affect tissue architecture and contribute to periodontal disease progression." (PMID 41502450, 2026).
preeclampsia (3 papers, 2014 to 2025). Preeclampsia is a hypertensive disorder of pregnancy that is characterized by new-onset hypertension with proteinuria presenting after 20 weeks of gestation, and depending on mild or severe forms may initially present with severe headache, visual disturbances, and hyperreflexia. "The most significant findings for an association with preeclampsia were the collagen, type I, alpha 1 (COL1A1) and IL1A genes for the maternal genotype and the plasminogen activator, urokinase receptor gene (PLAUR gene) for the offspring genotype." (PMID 24991435, 2014).
pterygium (3 papers, 2019 to 2022). A wedge-shaped fibrovascular lesion arising from the bulbar conjunctiva and extending to the cornea. "FN1 and the collagen family, including COL1A1, COL3A1, and COL4A1, were the components of ECM, involved in the fibrotic type of fibrosis and might be a group of significant genes in pterygium." (PMID 31341891, 2019).
renal carcinoma (3 papers, 2020 to 2025). A carcinoma arising from the epithelium of the renal parenchyma or the renal pelvis. "Previous investigations have indicated that COL1A1 and MMP13 are associated with cancer metastasis, and TM-induced apoptosis also showed close association with GRP78 and MMP13 in renal carcinoma cells." (PMID 33014334, 2020). "However, previous studies in patients with ovarian, gastric, pancreas, lung, and renal cancer or cell lines, indicated a profound expression of COL1A1 by CAFs or myofibroblasts." (PMID 38349551, 2024).
silicosis (3 papers, 2018 to 2021). Silicosis is a respiratory disease caused by breathing in (inhaling) silica dust. "We found that plasma HMGB-1 concentrations were positively correlated with COL1A1 (r = 0.21, p < 0.05) among silicosis patients." (PMID 30558126, 2018). "Moreover, the mice with silicosis following treatment of miR‐205‐5p agomir showed upregulated expression patterns of Col1a1, Col3a1 and LC3, while this upregulation was annulled by Lenti‐E2F1, Lenti‐SKP2 or siBeclin1." (PMID 34428336, 2021). "Compared with healthy controls, silicosis patients had remarkably higher plasma concentrations of matrix metalloproteinase-2 (MMP-2), matrix metalloproteinase-9 (MMP-9), collagen alpha-1(I) protein (COL1A1), and collagen alpha-1(III) protein (COL3A1) (all p < 0.05)." (PMID 30558126, 2018).
alveolar rhabdomyosarcoma (2 papers, 2018 to 2023). A rapidly growing malignant mesenchymal neoplasm. "The positive rate of PAX3–FOXO1 was 88.6% (31/35) in alveolar rhabdomyosarcoma, EWSR1–FLI1 was 63% (17/27) in pPNET, SYT–SSX was 95.4% in SS (62/65), ASPSCR1–TFE3 was 100% in ASPS (10/10), FUS–DDIT3 was 80% in MLPS (4/5), and COL1A1–PDGFB was 66.7% in DFSP (8/12)." (PMID 37621777, 2023).
Alzheimer disease (2 papers, 2019 to 2023). A progressive, neurodegenerative disease characterized by loss of function and death of nerve cells in several areas of the brain leading to loss of cognitive function such as memory and language. "In particular, genes such as Col1a1 Col1a2, Fmod, Ptgds, and Aldh1a2 are induced by exercise training and have been found to prevent hippocampal ageing in an Alzheimer’s disease model of animals with premature ageing." (PMID 31551509, 2019).
Amoebiasis (2 papers, 2022 to 2024). "The prime module in protein-protein interaction network of DEGs, including ADAMTS2, COL10A1, COL1A1, COL1A2, COL8A1, BGN, and SPP1, was enriched in protein digestion and absorption, ECM-receptor interaction, focal adhesion, PI3K-Akt signaling pathway, and amoebiasis." (PMID 35726219, 2022). "In detail, COL1A2, COL1A1, and COL10A1 were enriched in protein digestion and absorption; COL1A2, COL1A1, and SPP1 were enriched in ECM-receptor interaction, focal adhesion, and PI3K-Akt signaling pathway; COL1A2 and COL1A1 were further enriched in amoebiasis (P < 0.05)." (PMID 35726219, 2022).
Arthritis (2 papers, 2019 to 2022). Inflammation of a joint. "Only as arthritis subsided, Col1a1 was increased in Calcr−/− CAIA mice." (PMID 35036874, 2022).
Bruck syndrome (2 papers, 2014 to 2016). Bruck syndrome is characterized by the association of osteogenesis imperfecta and congenital joint contractures. "Interestingly, one type III OI sample from a patient with Bruck Syndrome showed COL1A1 and miR-29b expressions alike those from normal samples." (PMID 24767406, 2014). "Studies of Bruck syndrome have found normal secretion of collagen 1 in three families, whereas no mutations have been detected in the COL1A1 and COL1A2 genes." (PMID 24767406, 2014).
Cachexia (2 papers, 2021 to 2024). Severe weight loss, wasting of muscle, loss of appetite, and general debility related to a chronic disease. "Among the upregulated genes, Il6ra, Cdkn1a, Csf2rb2, and Akt1, and among the downregulated genes, Col1a1 and other collagen-related genes were involved in multiple pathways, suggesting their key function in cachexia." (PMID 34175899, 2021).
cardiac valvular EDS (2 papers, 2023 to 2025). "There are three different EDS types associated with pathogenic variants in the COL1A1 or COL1A2 genes: classical EDS with arterial fragility, arthrochalasis EDS, and cardiac valvular EDS." (PMID 40428297, 2025).
cervical squamous cell carcinoma (2 papers, 2023 to 2025). A squamous cell carcinoma arising from the cervical epithelium. "In contrast, low expression of COL1A1 was observed in cervical squamous cell carcinoma and endocervical adenocarcinoma (CESC), as well as uterine corpus endometrial carcinoma (UCEC)." (PMID 41040657, 2025). "POSTN + fibroblasts showed high expression levels of several ECM remodeling genes (MMP11, CTHRC1, COL1A1, COL1A2, COL3A1, COL10A1, and COL11A1) and enriched signatures of ECM, which were consistent with the previously reported matrix CAFs (mCAFs) in cervical squamous cell carcinoma (CESC)." (PMID 37833788, 2023).
chondrodysplasia (2 papers, 2021 to 2025). "In addition to variants in COL1A1 and COL1A2 associated with OI, many pathogenic variants in COL2A1 and COL10A1 are linked to chondrodysplasias." (PMID 33672767, 2021).
chronic hepatitis (2 papers, 2015 to 2020). An active inflammatory process affecting the liver for more than six months. "In addition, we also found that sesamin suppressed the expression of liver fibrosis markers like αSMA and Col1a1, suggesting that sesamin intake might improve chronic hepatitis dependent on ANX A1." (PMID 32133417, 2020).
colorectal adenocarcinoma (2 papers, 2021 to 2022). The most common type of colorectal carcinoma. "COL1A1 was overexpressed in tumor tissues from colorectal adenocarcinomas and its silencing significantly inhibited proliferation, migration and invasion, while cell apoptosis was promoted." (PMID 33648461, 2021). "Moreover, expression of the majority of the genes (CACNA1H, COL1A1, COL11A1, FZD8, NGFR, SFRP2, WNT2B, and WNT5A) was associated with the ‘mesenchymal’ CMS group 4 in the TCGA (The Cancer Genome Atlas) Colorectal Adenocarcinoma dataset." (PMID 35892888, 2022).
colorectal tumor (2 papers, 2021 to 2022). "Collagen type I alpha 1 chain (COL1A1) is confirmed to be an extracellular matrix protein that is overexpressed in many types of malignant tumors, including lung, breast, and colorectal tumors." (PMID 35842617, 2022).
diffuse large B-cell lymphoma (2 papers, 2020 to 2025). "Finally, certain lymphoproliferative diseases are also associated with expression of COL6A1, COL18A1, MMP3 and TIMP1, and a subset of patients with diffuse large B cell lymphoma and adverse prognosis show decreased expression of POSTN, SPARC, COL1A1, COL3A1,CSTK, MMP9 and LAMB3." (PMID 33379263, 2020).
emphysema (2 papers, 2024). "In a model of mice exposed to cigarette smoke to induce emphysema, reduced expression of COL1A1 and reduced collagen type I were observed in smoking mice as compared to controls." (PMID 39627862, 2024).
endothelial dysfunction (2 papers, 2022 to 2024). In vascular diseases, endothelial dysfunction is a systemic pathological state of the endothelium (the inner lining of blood vessels) and can be broadly defined as an imbalance between vasodilating and vasoconstricting substances produced by (or acting on) the endothelium. "Our results suggest that Orai1 and the downstream calmodulin/calcineurin/NFATC1/COL1A1 signaling pathway may play an important role in PTH-induced endothelial dysfunction and may be key potential therapeutic targets for preventing or treating SHPT-induced CVD." (PMID 35369318, 2022). "Consequently, these findings indicate that COL1A1, COL3A1, and POSTN could potentially be used as biomarkers to assess the severity of endothelial dysfunction in the progression of ED." (PMID 38467692, 2024).
glomerulonephritis (2 papers, 2021 to 2025). A renal disorder characterized by damage in the glomeruli. "Glomerulonephritis samples additionally showed expression of collagen (COL1A1) and immune cell markers for monocytes or macrophages (LYZ and CD163) and T cells (CD3D, CD3E and CD3G)." (PMID 41028563, 2025).